RNU1-30P (RNA, U1 small nuclear 30, pseudogene)
Gene: Small nuclear RNA gene on chromosome 3 (126,160,283 to 126,160,445, reverse strand). Ensembl gene ENSG00000272020.
Homologues: Orthologues: chimpanzee U1 (96% identical), macaque U1 (91% identical), mouse Gm23510 (83% identical). Paralogues in human: RNU1-1 (88% identical), RNU1-2 (88% identical), RNU1-27P (88% identical), RNU1-28P (88% identical), RNU1-3 (88% identical), RNU1-4 (88% identical), RNVU1-18 (88% identical), RNVU1-29 (88% identical), U1 (88% identical), RNU1-89P (87% identical), RNVU1-28 (87% identical), RNVU1-7 (87% identical), and 134 more.